GRIN2B (glutamate ionotropic receptor NMDA type subunit 2B)
Description:
Component of N-methyl-D-aspartate (NMDA) receptors (NMDARs) that function as heterotetrameric, ligand-gated cation channels with high calcium permeability and voltage-dependent block by Mg(2+). Participates in synaptic plasticity for learning and memory formation by contributing to the long-term depression (LTD) of hippocampus membrane currents (By similarity). Channel activation requires binding of the neurotransmitter L-glutamate to the GluN2 subunit, glycine or D-serine binding to the GluN1 subunit, plus membrane depolarization to eliminate channel inhibition by Mg(2+). NMDARs mediate simultaneously the potassium efflux and the influx of calcium and sodium (By similarity). Each GluN2 subunit confers differential attributes to channel properties, including activation, deactivation and desensitization kinetics, pH sensitivity, Ca2(+) permeability, and binding to allosteric modulators. In concert with DAPK1 at extrasynaptic sites, acts as a central mediator for stroke damage. Its phosphorylation at Ser-1303 by DAPK1 enhances synaptic NMDA receptor channel activity inducing injurious Ca2+ influx through them, resulting in an irreversible neuronal death (By similarity).
Synonyms: GluN2B; NMDAR2B; NR2B; NR3; hNR3; DEE27; EIEE27; MRD6
Tractability: Small molecule: an approved drug acts on it; a structure with a bound ligand is known; a high-quality ligand is known; it belongs to a druggable protein family. Antibody: UniProt places it where antibodies can reach, with high confidence; its Gene Ontology location is reachable by antibodies, with high confidence; UniProt predicts a signal peptide or a membrane-spanning region. PROTAC: its protein half-life has been measured; a small molecule that binds it is known. Other modalities: a drug acting on it is in phase 2 or 3 trials.
Target class: Ion channel; Ionotropic glutamate receptor; Ligand-gated ion channel; NMDA receptor
Chemical probes: CHEMBL48029
Safety:
Unwanted effects reported when the protein is acted on. In parentheses: how it was acted on, where the effect was seen, and who reports it.
ataxia (inhibition, acute dosing; central nervous system, cardiovascular; source: Lynch et al. (2017))
convulsions (activation, acute dosing; central nervous system, cardiovascular; source: Lynch et al. (2017))
decreased convulsions (inhibition, acute dosing; central nervous system, cardiovascular; source: Lynch et al. (2017))
decreased memory (inhibition, acute dosing; central nervous system, cardiovascular; source: Lynch et al. (2017))
decreased pain (inhibition, acute dosing; central nervous system, cardiovascular; source: Lynch et al. (2017))
dizziness (inhibition, acute dosing; central nervous system, cardiovascular; source: Lynch et al. (2017))
drug abuse/dependence (inhibition, acute dosing; central nervous system, cardiovascular; source: Lynch et al. (2017))
impaired social interactions (inhibition, chronic dosing; central nervous system, cardiovascular; source: Lynch et al. (2017))
increased blood pressure (inhibition, acute dosing and activation, acute dosing; central nervous system, cardiovascular; source: Lynch et al. (2017))
increased heart rate (inhibition, acute dosing; central nervous system, cardiovascular; source: Lynch et al. (2017))
increased locomotor activity (inhibition, acute dosing; central nervous system, cardiovascular; source: Lynch et al. (2017))
increased then decreased heart rate (activation, acute dosing; central nervous system, cardiovascular; source: Lynch et al. (2017))
neurodegeneration (inhibition, chronic dosing; central nervous system, cardiovascular; source: Lynch et al. (2017))
neurotoxicity (inhibition, acute dosing; central nervous system, cardiovascular; source: Lynch et al. (2017))
pain (activation, acute dosing; central nervous system, cardiovascular; source: Lynch et al. (2017))
psychosis (inhibition, chronic or acute dosing; central nervous system, cardiovascular; source: Lynch et al. (2017))
stereotypy (inhibition, chronic dosing; central nervous system, cardiovascular; source: Lynch et al. (2017))
adverse reactions (source: ClinPGx)
neurological adverse reactions (source: ClinPGx)
neurological adverse reactions and sleepiness (source: ClinPGx)
sleepiness (source: ClinPGx)
Gene: Protein-coding gene on chromosome 12 (13,437,942 to 13,982,002, reverse strand). Ensembl gene ENSG00000273079.
Subcellular location: Cell membrane; Postsynaptic cell membrane; Cell projection, dendrite; Late endosome; Lysosome; Cytoplasm, cytoskeleton
Subcellular location (Human Protein Atlas): Plasma membrane; Basal body; Nucleoplasm; Primary cilium; Primary cilium tip; Primary cilium transition zone
Pathways (Reactome):
Neuronal System: Assembly and cell surface presentation of NMDA receptors; Long-term potentiation; Negative regulation of NMDA receptor-mediated neuronal transmission; Neurexins and neuroligins; Ras activation upon Ca2+ influx through NMDA receptor; Synaptic adhesion-like molecules; Unblocking of NMDA receptors, glutamate binding and activation
Signal Transduction: Activated NTRK2 signals through FYN; RAF/MAP kinase cascade
Developmental Biology: EPHB-mediated forward signaling
Gene Ontology:
Molecular function: glutamate-gated calcium ion channel activity; glycine binding; ligand-gated monoatomic ion channel activity involved in regulation of presynaptic membrane potential; NMDA glutamate receptor activity; protein binding; amyloid-beta binding; glutamate binding; transmitter-gated monoatomic ion channel activity involved in regulation of postsynaptic membrane potential; zinc ion binding; ligand-gated monoatomic ion channel activity; monoatomic ion channel activity; signaling receptor activity
Biological process: calcium ion transmembrane import into cytosol; monoatomic cation transmembrane transport; response to ethanol; brain development; chemical synaptic transmission; excitatory chemical synaptic transmission; excitatory postsynaptic potential; glutamate receptor signaling pathway; ionotropic glutamate receptor signaling pathway; learning or memory; long-term synaptic potentiation; negative regulation of dendritic spine maintenance; positive regulation of excitatory postsynaptic potential; positive regulation of synaptic transmission, glutamatergic; protein heterotetramerization; regulation of monoatomic cation transmembrane transport; regulation of neuronal synaptic plasticity; regulation of synaptic plasticity; synaptic transmission, glutamatergic; calcium-mediated signaling; monoatomic ion transport; regulation of membrane potential; regulation of presynaptic membrane potential
Cellular component: ciliary tip; ciliary transition zone; cilium; NMDA selective glutamate receptor complex; plasma membrane; cell surface; cytoplasm; endoplasmic reticulum membrane; late endosome; lysosome; neuron projection; postsynaptic density; postsynaptic density membrane; postsynaptic membrane; synaptic membrane; cytoskeleton; dendrite; membrane
Genetic constraint (gnomAD): Loss-of-function variants: 5 observed, 103.29 expected, observed/expected ratio (o/e) 0.0484, 90% interval 0.024 to 0.1. The upper end of that interval is the gene's LOEUF score, 0.1, which puts it in group 1 of 6, group 1 being the genes least tolerant of losing a copy. Missense variants: 1,071 observed, 1,961.3 expected, observed/expected ratio (o/e) 0.55, 90% interval 0.52 to 0.57. Synonymous variants: 762 observed, 763.07 expected, observed/expected ratio (o/e) 1, 90% interval 0.94 to 1.06.
Gene-disease validity (ClinGen):
ClinGen rates the evidence that GRIN2B causes each of these diseases.
complex neurodevelopmental disorder (autosomal dominant): Definitive. A disorder that involves more than one phenotype associated with the central nervous system, including but not limited to intellectual disability, autism, and seizures (epilepsy).
Homologues: Orthologues: chimpanzee GRIN2B (99% identical), macaque GRIN2B (99% identical), rabbit GRIN2B (99% identical), rat Grin2b (99% identical), mouse Grin2b (99% identical), dog GRIN2B (98% identical), pig GRIN2B (98% identical), guinea pig GRIN2B (89% identical), tropical clawed frog grin2b (84% identical), zebrafish grin2bb (72% identical), zebrafish grin2ba (65% identical), Drosophila melanogaster Nmdar2 (19% identical), and 38 more. Paralogues in human: GRIN2A (51% identical), GRIN2C (36% identical), GRIN2D (34% identical), GRIN3A (17% identical), GRIN3B (17% identical), GRIN1 (14% identical), GRIK1 (14% identical), GRIK5 (13% identical), GRIA4 (13% identical), GRIK3 (13% identical), GRIK2 (13% identical), GRIA3 (13% identical), and 5 more.
Diseases named in the same sentence as GRIN2B in open-access papers:
GRIN2B is named in the same sentence as 239 diseases in open-access papers, as found by Europe PMC text mining. Sharing a sentence is not in itself a finding about the gene and the disease. The quoted sentences say what the papers report.
schizophrenia (102 papers, 2008 to 2026). A major psychotic disorder characterized by abnormalities in the perception or expression of reality. "GRIN2B variants arising from missense, nonsense, frameshift, or splice site mutations are frequently associated with NDDs such as autism, schizophrenia, DD/ID, and epileptic encephalopathy." (PMID 39596430, 2024). "Mutations and epimutations to GRIN2B have been associated with risk for neurological diseases including attention-deficit/hyperactivity disorder, autism spectrum disorders, and schizophrenia." (PMID 39775235, 2024). "Mutations in this gene cause GRIN2B-related neurodevelopmental disorder, and variants are associated with risk for schizophrenia, autism spectrum disorder, and attention-deficit/hyperactivity disorder." (PMID 39775235, 2024). "SNPs of SLC1A1 (rs2228622) and GRIN2B (rs890) genes as well as the interaction between the two genes showed a tendency for association with OCS in schizophrenia patients receiving clozapine." (PMID 37627285, 2023). "We previously showed that the GRIN2A and GRIN2B genes are associated with early onset of schizophrenia." (PMID 36980845, 2023). "The GRIN2A and GRIN2B genes are being extensively studied as plausible candidate genes for the susceptibility to schizophrenia and other neurodegenerative or neurodevelopmental disorders." (PMID 36980845, 2023). "GRIN2A rs11644461*T and GRIN2B rs7313149*T alleles have protective effect against developing the continuous type of schizophrenia." (PMID 36980845, 2023). "Recently, we demonstrated an association of the GRIN2B rs7313149 with the early manifestation of schizophrenia." (PMID 36980845, 2023). "Although, these GRIN2A and GRIN2B genes are also susceptible to early onset of schizophrenia function as well as to attentional impairment in ADHD (attention-deficit/hyperactivity disorder) and HD." (PMID 35958988, 2022). "The GRIN2A and GRIN2B genes are being actively investigated as candidate genes for the predisposition of schizophrenia and other neurodevelopmental and/or neurodegenerative disorders." (PMID 34685369, 2021). "In this study, we examined the contribution of GRIN2A and GRIN2B (Glutamate Ionotropic Receptor NMDA Type Subunit 2A/2B) polymorphisms to the clinical features of schizophrenia, such as the leading symptoms, the type of course, and the age of onset." (PMID 34685369, 2021). "At the same time, we were the first to obtain data on the association of the GRIN2A (rs7206256, rs11644461) and GRIN2B (rs7313149) genes with early onset of schizophrenia in the Russian population of the Siberian region." (PMID 34685369, 2021). "Earlier, we studied the role of GRIN2A and GRIN2B variants in antipsychotic-induced tardive dyskinesia in schizophrenia in terms of genetically determined increase in vulnerability to NMDA-induced excitotoxicity." (PMID 34685369, 2021). "Single nucleotide or dinucleotide-repeated polymorphisms of the NMDAR subunit genes, such as NR1 (GRIN1), NR2A (GRIN2A), and NR2B (GRIN2B), increase susceptibility to schizophrenia." (PMID 31417356, 2019). "Further studies revealed that variations in the GRIN2B were associated with schizophrenia, psychiatric disorders, and brain plasticity." (PMID 31018568, 2019). "Further studies revealed that variations in the NMDAR 2B subunit gene (GRIN2B) were associated with schizophrenia, psychiatric disorders, and brain plasticity." (PMID 26819771, 2016). "An Danish study found 9 SNPs (rs890, rs1806191, rs10772692, rs2270359, rs1806194, rs1806195, rs1805482, rs1805199 and rs1805554) out of 30 in GRIN2B were significantly associated with schizophrenia population." (PMID 26257337, 2015). "Several studies have shown associations between SNPs of GRIN2A and/or GRIN2B and neurological or psychiatric diseases, such as Huntington’s disease, schizophrenia, bipolar disorder and Alzheimer’s disease." (PMID 23408766, 2013).
schizophrenia (continued). "For example, an excess of missense variants has been reported in the gene GRIN2B, encoding the NMDA receptor subunit NR2B, in schizophrenia and autism but also with other neurodevelopmental phenotypes." (PMID 22078159, 2011). "Similarly, cognitive decline in patients with schizophrenia has been linked to altered methylation levels in the GRIN2B gene promoter." (PMID 40438331, 2025). "The reduced GRIN2A/GRIN2B ratio in these studies may therefore be more likely to be associated with schizophrenia or psychosis." (PMID 41465140, 2025). "Genetic variation in the GRIN2B gene has also been reported to be associated with schizophrenia." (PMID 29520222, 2018). "In the present study, GRIN2B rs890 showed significant associations with schizophrenia." (PMID 26257337, 2015). "For example, a mutation analysis of GRIN2B in Japanese population found that only rs7301328(366C/G) polymorphism in the 3′ region of the last exon was statistically significant assosiated with schizophrenia." (PMID 26257337, 2015). "Stronger data may actually support an interaction between these genes, i.e., GRIN1A plus GRIN2B, and the interactions between abnormal genes and their resultant proteins may actually convey greater risk for schizophrenia than any single gene alone." (PMID 23189055, 2012). "Moreover, reported associations of GRIN2B polymorphisms and schizophrenia have been published." (PMID 36980845, 2023). "In addition, GRIN2B variants have been associated with autism spectrum disorder and schizophrenia." (PMID 34685369, 2021). "The aim of the study was to explore whether selected nucleotide variants in GRIN1, GRIN2A, and GRIN2B encoding subunits of the N-methyl-d-aspartate receptor (NMDA-R) receptor occur in a selected group of patients with treatment resistant schizophrenia with cognitive impairment." (PMID 33025395, 2021). "For instance, in patients with schizophrenia, an overall reduction in methylation at five CpG sites in the GRIN2B gene promoter was observed, with methylation levels at CpG4 positively correlating with cognitive outcomes." (PMID 40438331, 2025). "A deficiency in PACAP, commonly seen in schizophrenia, likely reduces NMDA receptor activity, particularly in SST interneurons, which are highly enriched with PACAP receptors and GRIN2B subunits." (PMID 39596430, 2024). "We found nominally significant (p < 0.05) associations with the continuous course of schizophrenia for the following polymorphisms: GRIN2A rs11644461, rs8057394; GRIN2B rs7313149." (PMID 36980845, 2023). "We examined the association of 39 single nucleotide polymorphisms in eight genes (GRIN2A, GRIN2B, SLC1A2, SLC1A3, SLC17A7, GRM3, GRM7, and GRM8) involved in the glutamatergic system with the development of clinical heterogeneity of schizophrenia." (PMID 36980845, 2023). "In the cortex, Grin2b is involved in the regulation of dendritic spine maintenance and neuron death, and the expression of Grin2b was up-regulated in the prefrontal cortex of a schizophrenia rat model." (PMID 37138704, 2023). "In our study, we identified an association of GRIN2A rs7206256*A, GRIN2A rs1164446*GG/G, and GRIN2B rs7313149*A with the early onset of schizophrenia." (PMID 34685369, 2021). "GRIN1, GRIN2A, GRIN2B, GRIN2C, and GRIN2D all encode subunits of the N-methyl-D-aspartate receptor (NMDAR), which has been shown to be involved in the development of schizophrenia." (PMID 34946799, 2021). "In addition to ASD, GRIN2B has been extensively associated with various neurodevelopmental disorders, including developmental delay, intellectual disability, attention-deficit/hyperactivity disorder, epilepsy, schizophrenia, obsessive-compulsive disorder, and encephalopathy." (PMID 32353004, 2020). "Genome wide significant associations with schizophrenia have been reported for at least two of the NMDAR genes- GRIN2A and GRIN2B." (PMID 29520222, 2018).